POR (cytochrome p450 oxidoreductase)
Description:
This enzyme is required for electron transfer from NADP to cytochrome P450 in microsomes. It can also provide electron transfer to heme oxygenase and cytochrome B5.
Synonyms: CPR; P450R; CYPOR; FLJ26468
Tractability: Small molecule: a structure with a bound ligand is known; it has a binding pocket of medium quality. Antibody: UniProt predicts a signal peptide or a membrane-spanning region. PROTAC: ubiquitination databases record sites on it; its protein half-life has been measured; a small molecule that binds it is known.
Target class: Enzyme; Oxidoreductase
Safety:
Unwanted effects reported when the protein is acted on. In parentheses: how it was acted on, where the effect was seen, and who reports it.
new-onset diabetes after transplantation (source: ClinPGx)
Gene: Protein-coding gene on chromosome 7 (75,899,200 to 75,986,855, forward strand). Ensembl gene ENSG00000127948.
Subcellular location: Endoplasmic reticulum membrane
Subcellular location (Human Protein Atlas): Vesicles; Cytosol; Nucleoplasm
Pathways (Reactome):
Metabolism: Cytochrome P450 - arranged by substrate type
Gene Ontology:
Molecular function: enzyme activator activity; NADPH-hemoprotein reductase activity; protein binding; flavin adenine dinucleotide binding; FMN binding; cytochrome-b5 reductase activity, acting on NAD(P)H; electron transfer activity; enzyme binding; hydrolase activity; iron-cytochrome-c reductase activity; NADP binding; nitric oxide dioxygenase NAD(P)H activity; oxidoreductase activity
Biological process: electron transport chain; organofluorine metabolic process; nitric oxide biosynthetic process; P450-containing electron transport chain; response to hormone; carnitine metabolic process; cellular response to follicle-stimulating hormone stimulus; cellular response to gonadotropin stimulus; cellular response to peptide hormone stimulus; demethylation; fatty acid oxidation; negative regulation of apoptotic process; nitrate catabolic process; nitric oxide catabolic process; positive regulation of chondrocyte differentiation; positive regulation of growth plate cartilage chondrocyte proliferation; positive regulation of smoothened signaling pathway; positive regulation of steroid hormone biosynthetic process; response to dexamethasone; response to nutrient; response to xenobiotic stimulus
Cellular component: cytosol; intracellular membrane-bounded organelle; membrane; nucleoplasm; endoplasmic reticulum membrane; cytoplasm
Genetic constraint (gnomAD): Loss-of-function variants: 56 observed, 78.88 expected, observed/expected ratio (o/e) 0.71, 90% interval 0.57 to 0.89. The upper end of that interval is the gene's LOEUF score, 0.89, which puts it in group 3 of 6, group 1 being the genes least tolerant of losing a copy. Missense variants: 938 observed, 908.69 expected, observed/expected ratio (o/e) 1.03, 90% interval 0.98 to 1.09. Synonymous variants: 414 observed, 377.56 expected, observed/expected ratio (o/e) 1.1, 90% interval 1.01 to 1.19.
Gene-disease validity (ClinGen):
ClinGen rates the evidence that POR causes each of these diseases.
Antley-Bixler syndrome with genital anomalies and disordered steroidogenesis (autosomal recessive): Definitive.
Homologues: Orthologues: chimpanzee POR (99% identical), macaque POR (99% identical), dog POR (94% identical), chimpanzee POR (93% identical), rat Por (93% identical), pig POR (92% identical), mouse Por (92% identical), guinea pig POR (91% identical), tropical clawed frog por (80% identical), zebrafish porb (74% identical), zebrafish pora (71% identical), Drosophila melanogaster Cpr (57% identical), and 2 more. Paralogues in human: NOS1 (30% identical), NOS2 (30% identical), MTRR (30% identical), NOS3 (30% identical), NDOR1 (27% identical).
Diseases named in the same sentence as POR in open-access papers:
POR is named in the same sentence as 98 diseases in open-access papers, as found by Europe PMC text mining. Sharing a sentence is not in itself a finding about the gene and the disease. The quoted sentences say what the papers report.
congenital adrenal hyperplasia (25 papers, 2013 to 2026). Congenital adrenal hyperplasia (CAH) is an inherited endocrine disorder caused by a steroidogenic enzyme deficiency that is characterized by adrenal insufficiency and variable degrees of hyper or hypo androgyny manifestations, depending of the type and the severity of the disease. "Mutations in POR lead to metabolic disorders, including congenital adrenal hyperplasia, and affect the metabolism of steroids, drugs, and xenobiotics." (PMID 38136599, 2023). "Studies of the steroid profile of patients with congenital adrenal hyperplasia due to deficiencies of 17α-, 11β- or 21-hydroxylase (and POR), corroborate this physiological data, reinforcing the concept of a “MC (or non-17-hydroxylated) pathway of ZF”." (PMID 35263051, 2022). "The present study shows that polymorphisms in the POR gene are associated with the phenotype of patients with congenital adrenal hyperplasia, a novel finding in the pathophysiology of 21 hydroxylase deficiency." (PMID 33666875, 2021). "Clinicians were struck by the mild, non-progressive virilization in context of severe, salt-wasting 21 hydroxylase deficiency suggesting an impact of the heterozygous POR defect on clinical features of congenital adrenal hyperplasia." (PMID 33666875, 2021). "Our data now provide evidence for the association between POR polymorphisms and clinical features of congenital adrenal hyperplasia, thereby establishing POR as a genetic modifier of CYP21A2 defects." (PMID 33666875, 2021). "In conclusion, our study demonstrated that POR acts as a modifier gene in congenital adrenal hyperplasia due to 21 hydroxylase deficiency." (PMID 33666875, 2021). "Defects in POR genes have been proven to cause a variety of symptoms, from embryonic lethality to disordered steroidogenesis, congenital adrenal hyperplasia, ambiguous genitalia, and Antley-Bixler syndrome." (PMID 29232835, 2017). "P450 oxidoreductase deficiency (PORD) is a variant of congenital adrenal hyperplasia that is caused by POR gene mutations." (PMID 27737328, 2016). "Knockout of POR gene is early embryonic lethal in mice, while mutations and polymorphisms in humans are connected with disordered steroidogenesis, congenital adrenal hyperplasia, Antley-Bixler or Williams syndromes." (PMID 24642534, 2014). "Inactivating mutations in POR gene is responsible for the congenital adrenal hyperplasia (CAH) manifesting with apparent combined CYP17A1-CYP21A2 deficiency." (PMID 24376526, 2013). "In humans, the most severe POR mutations cause a loss of cofactor binding sites in the enzyme, leading to near inactivation of POR and P450 oxidoreductase deficiency disorder, a form of congenital adrenal hyperplasia." (PMID 38300925, 2024). "Aim of the present study is to evaluate whether genomic variants in POR contribute to the phenotype of patients with congenital adrenal hyperplasia due to CYP21A2 mutations." (PMID 33666875, 2021). "Congenital adrenal hyperplasia (CAH) caused by a mutation in the P450 oxidoreductase (POR) gene is a rare, autosomal recessive disorder." (PMID 41283580, 2025). "P450 oxidoreductase deficiency (PORD) is a rare autosomal recessive variant of congenital adrenal hyperplasia (CAH) arising from homozygous or compound heterozygous POR gene mutations." (PMID 33526062, 2021). "POR mutations cause a complex spectrum of disorders, including defects in P450C17 and P450C21, amenorrhea, disordered steroid hormone production, congenital adrenal hyperplasia, and Aintree–Bixler syndrome." (PMID 40504108, 2026). "Congenital adrenal hyperplasia (CAH) is a group of autosomal recessive disorders caused by pathogenic variants identified in seven genes (CYP21A2, CYP11B1, CYP17A1, HSD3B2, StAR, POR, and CYP11A1) involved in the steroidogenesis pathway." (PMID 39451515, 2024).
congenital adrenal hyperplasia (continued). "Congenital adrenal hyperplasia (CAH) refers to a group of seven monogenic adrenal disorders, caused by pathological variants in genes coding for enzymes in the adrenal steroidogenic pathway: CYP21A2, CYP11B1, CYP17A1, HSD3B2, STAR, CYP11A1, and POR." (PMID 41450580, 2025). "Polymorphisms in the POR gene are associated with clinical features of 21 hydroxylase deficiency both as regards predisposition to classic vs non-classic forms and severity of classic adrenal hyperplasia." (PMID 33666875, 2021). "Congenital adrenal hyperplasia (CYP21A2, CYP11B1, HSD3B2, CYP17A1, POR defects) constitutes the largest subgroup of impaired steroidogenesis and represents the most common cause of PAI in children." (PMID 27485500, 2016). "The mutation-driven changes in the 3D structure of the POR enzyme could lead to a medical condition known as cytochrome P450 oxidoreductase deficiency (PORD) (OMIM: 613571), which is an autosomal recessive genetic disorder and can also be categorized as a rare congenital adrenal hyperplasia (CAH)." (PMID 35889519, 2022). "Defects of CYP21A2 secondary to POR mutations may lead to potential deficiency of cortisol and mild increase in pituitary production of adrenocorticotrophic hormone (ACTH) commonly without obvious signs of adrenal hyperplasia detected on adrenal imaging." (PMID 37635957, 2023).
Antley-Bixler syndrome (13 papers, 2012 to 2025). Antley-Bixler syndrome is a very rare disorder characterized by craniosynostosis with midface hypoplasia, radiohumeral synostosis, femoral bowing and joint contractures. "Homozygous mutations in the POR gene, encoding cytochrome P450 oxidoreductase, induce midface hypoplasia and craniosynostosis in Antley-Bixler syndrome, accompanied by genital anomalies and disordered steroidogenesis (OMIM #201750)." (PMID 32850826, 2020). "In case 7 (angular femoral deformity and ventricular septal defect), two compound heterozygous causative mutations in the POR gene were detected: c.1370G > A (p.Arg457His) and c.744C > G (p.Tyr248*), which were associated with the Antley-Bixler syndrome." (PMID 31299979, 2019). "These mutations in POR (e.g., Y181D, A287P, A115V and G413) are associated with Antley-Bixler Syndrome, and A287P was found to be the most common POR mutation in the European population." (PMID 22719896, 2012). "Human patients with specific mutations in POR exhibit severe developmental malformations including disordered steroidogenesis, sexual ambiguities and various bone defects, similar to those seen in patients with Antley-Bixler syndrome (ABS)." (PMID 24086598, 2013). "In patients with the Antley-Bixler syndrome, characterized by craniosynostosis, brachycephaly, midface hypoplasia, and choanal atresia and/or stenosis, variants have been found not only in FGFR2, but also in the gene encoding cytochrome p450 oxidoreductase (POR)." (PMID 37441579, 2023). "For example for patients with Antley-Bixler syndrome (OMIM 201750), a disorder characterized by severe developmental abnormalities and exhibiting considerable numbers of different haplotypes of the POR gene." (PMID 29104319, 2017).
hepatoma (8 papers, 2015 to 2023). "Deficiency of POR leads to blockage of the sterol synthesis pathway at lanosterol demethylase (CYP51) resulting in the accumulation of lanosterol in hepatocytes of hepatic POR-null mice or in rat hepatoma cells with suppression of POR expression by siRNA." (PMID 34867397, 2021). "In the present study we used human hepatoma HepG2 cells carrying a knockout (KO) in the POR gene as a human in vitro model that can mimic the HRN mouse model." (PMID 32265041, 2020). "The endogenous expression of H-rev107 and POR was confirmed by western blotting in cells derived from HtTA cells and Huh7 hepatoma cells." (PMID 26381418, 2015). "In order to investigate whether the phenomenon observed in POR KO Hepa1c1c7 cells extends to human cells, we have now conducted a study in the human hepatoma cell line HepG2." (PMID 32265041, 2020). "Although the impact of pregnancy or PRHs on POR has not been studied to date, our observation that PRHs and nuclear receptor activators increased POR in SCHH was consistent with prior reports that GR and PXR activators induced Por mRNA levels in a rat hepatoma cell line." (PMID 36210832, 2022). "Previously we created mouse hepatoma Hepa1c1c7 cells lacking POR expression using CRISPR/Cas9 technology." (PMID 32265041, 2020).
breast carcinoma (5 papers, 1999 to 2023). "Kalafungin and nanaomycin analogues show specificity towards breast cancer cell lines over-expressing cytochrome P450 oxidoreductase with cytotoxicity diminished under anoxia, where reactive oxygen production is inhibited." (PMID 37446864, 2023).
21-hydroxylase deficiency (4 papers, 2021 to 2025). "Although pathogenic variants have been identified in several genes, including CYP11B1, CYP17A1, HSD3B2, POR, STAR, and CYP11A1, approximately 95% of CAH cases are caused by 21-hydroxylase deficiency (21-OHD), primarily due to mutations in the CYP21A2 gene." (PMID 41440812, 2025). "None of the other POR polymorphisms or the 868/194 haplotype were associated with clinical features of classic or non-classic 21 hydroxylase deficiency." (PMID 33666875, 2021). "None of the other POR polymorphisms or haplotypes were associated with increased risk of either classic or non-classic 21 hydroxylase deficiency or CYP21A2 defect grouping." (PMID 33666875, 2021). "Sequencing of the POR gene was performed in 96 patients with 21 hydroxylase deficiency (49 classic, 47 non-classic) and 43 control subjects." (PMID 33666875, 2021). "Given that the POR gene is located on chromosome 7 and CYP21A2 on chromosome 6, linkage disequilibrium between rs2228104 and CYP21A2 mutations associated with non-classic 21 hydroxylase deficiency appears unlikely." (PMID 33666875, 2021).
malaria (4 papers, 2011 to 2024). Malaria is a serious and sometimes fatal disease caused by a parasite that commonly infects a certain type of mosquito which feeds on humans. "P450 liver enzymes and heme oxygenase involving in drug metabolism need POR to provide electrons, therefore, the mutation of POR gene or associated SNPs may affect drug metabolism in human body and affect the progression of some diseases such as malaria and sepsis." (PMID 28288674, 2017). "NADPH-cytochrome P450 oxidoreductase (CPR) plays a central role in chemicaldetoxification and insecticide resistance in Anopheles gambiae,the major vector for malaria." (PMID 21655236, 2011).
Sepsis (4 papers, 2017 to 2025). Sepsis is defined as life-threatening organ dysfunction caused by a dysregulated host response to infection. "Recent studies showed that NOX4 was characterized in the cardiovascular system, HMOX1 can be induced by sepsis, and POR was selected as the central gene of SIC." (PMID 37035738, 2023). "In a recent bioinformatics analysis of sepsis-induced cardiomyopathy, POR was selected as the central gene and its expression level was higher than that of the control group." (PMID 37035738, 2023). "It was also reported that cuproptosis-related genes (POR, SLC7A5, and STAT3) or N6-methyladenosine (m6A) methylation were strongly involved in the pathological process of sepsis-induced cardiomyopathy." (PMID 39427197, 2024). "The ferroptosis-related genes (NOX4, HMOX1, POR, SAT1, etc.)were highly expressed in sepsis-induced cardiomyopathy model." (PMID 37035738, 2023).
Infertility (3 papers, 2020 to 2023). "By reviewing data from 48 articles including 119 patients from around the world, the present study aims to show the gender- and genotype-related prevalence of CAH, DSD, TARTs, and infertility in patients with heterozygous or homozygous POR gene variants." (PMID 35842891, 2023). "We report a live birth from a Chinese woman who presented with primary amenorrhea and infertility caused by a compound heterozygote POR mutation." (PMID 33526062, 2021). "A 29-year-old Chinese woman with PORD due to the compound heterozygous mutation (c.1370G > A/c.1196_1204del) in the P450 oxidoreductase (POR) gene had suffered from primary amenorrhea and infertility." (PMID 33526062, 2021). "The unknown prevalence of POR gene pathogenetic variants and the paucity of studies investigating fertility do not allow us to establish whether PORD is associated with infertility." (PMID 35842891, 2023). "In conclusion, the unknown incidence of POR gene variants and the poorness of fertility-investigating reports enlighten that it is still unclear whether PORD is associated with human infertility since most of the cases reported so far did not focus on patients’ fertility." (PMID 35842891, 2023).
lung carcinoma (3 papers, 2021 to 2025). "Although enzymes like cytochrome P450 oxidoreductase (POR) and NADPH oxidases (NOXs) also participate in lipid peroxidation during ferroptosis, their possible effects on lung cancer cells have not been determine." (PMID 34742351, 2021).
acute myeloid leukemia (2 papers, 2013 to 2020). Acute myeloid leukemia (AML) is a group of neoplasms arising from precursor cells committed to the myeloid cell-line differentiation. "This study detected 60 gene-encoding proteins participating in drug metabolism and efflux, with the POR gene and daunorubicin (DNR) showing the strongest cardiotoxic effects in patients with acute myeloid leukemia (AML)." (PMID 33110473, 2020).
adrenocortical insufficiency (2 papers, 2017 to 2022). An endocrine or hormonal disorder that occurs when the adrenal cortex does not produce enough of the hormone cortisol and in some cases, the hormone aldosterone. "POR mutation can result in various clinical manifestations, including pseudohermaphroditism at birth, skeletal deformity, maternal hyperandrogenism during pregnancy, and adrenocortical insufficiency." (PMID 36518257, 2022). "Activities of different POR mutants for target enzymes would have a certain role in variability of adrenocortical insufficiency." (PMID 28288674, 2017).
bladder cancer (2 papers, 2015 to 2018). "In conclusion, we found that POR A503V has a significantly association with bladder cancer risk among the Chinese population." (PMID 26123203, 2015). "Although the associations between POR variants and human disease have been occasionally reported, very few studies have investigated the relationship between POR variants and human bladder cancer." (PMID 26123203, 2015). "The present study demonstrated that A503V POR might decrease bladder cancer risk by reducing its electron transfer activity or exogenous and endogenous substrate metabolism." (PMID 26123203, 2015). "The results suggested that POR A503V might decrease the risk of bladder cancer by reducing its metabolic activity, and should be a potential biomarker for predicting the susceptibility to human bladder cancer." (PMID 26123203, 2015). "However, few studies have explored the association between POR variants and the risk of bladder cancer." (PMID 26123203, 2015). "To test this hypothesis, we genotyped POR gene polymorphisms in the coding region and explored their relation to the risk of bladder cancer in our ongoing, hospital-based, case-control study in a Chinese population." (PMID 26123203, 2015). "Therefore, the POR A503V might contribute to a decrease in the catalytic activity of P450c17 and subsequent androgen formation, which may ultimately attenuate bladder cancer risk." (PMID 26123203, 2015). "The POR A503V variant-mediated decrease in metabolic CYP3A4 activation would generate decreased 2’-hydroxylated NNN and possibly reduce bladder cancer risk." (PMID 26123203, 2015). "To date, no study between POR variants and bladder cancer risk has been reported." (PMID 26123203, 2015).